INS (insulin)
Diseases named in the same sentence as INS in open-access papers (continued):
Sharing a sentence is not in itself a finding about the gene and the disease.
Insulin resistance (continued). "Finally, insulin resistance induced by recombinant GH appeared to be reversible, as insulin levels declined upon discontinuation of treatment, although remained above pre-treatment levels." (PMID 36875465, 2023). "Furthermore, previous findings suggest that selective insulin resistance occurs despite intact hepatic insulin signaling." (PMID 36920797, 2023). "Similarly, the role of insulin in regulating adipocyte function contributes to the close link between insulin resistance and obesity." (PMID 34167604, 2023). "Insulin resistance can manifest as a reduction in insulin sensitivity (the insulin concentration that induces a half-maximal response), a reduction in insulin responsiveness (the maximal effect of insulin on insulin-sensitive tissues), or both simultaneously." (PMID 38274826, 2023). "Given the complex biological mechanisms involved in the BCAA metabolism and its close link with insulin resistance, further MR studies in large numbers of pregnancies to dissect the impact of maternal fasting insulin and circulating BCAAs on offspring birthweight are warranted." (PMID 36696816, 2023). "Smoking results in insufficient secretion of insulin and insulin resistance via ß-cell dysfunction, oxidative stress, inflammation, and increased level of C reactive protein (CRP) that may promote the risk of cardio-metabolic dysfunction." (PMID 37237334, 2023). "Additionally, while insulin resistance is classically thought to result from defective insulin signalling, phosphoproteomics has uncovered numerous emergent phosphosites, featuring enhanced or novel insulin responses in insulin resistance." (PMID 37248992, 2023). "Importantly, these positive effects are consistent with an improved metabolic profile, including serum insulin levels and Homeostatic Model Assessment for Insulin Resistance (HOMA-IR)." (PMID 36839303, 2023). "First, individuals with a genetic susceptibility to T2DM are more likely to be obese because the inherent insulin resistance in the muscle and islet α-cells of these individuals leads to increased glucose and insulin release in the liver, which results in obesity." (PMID 37810434, 2023). "In addition, CRP in the perinatal period predicted higher absolute insulin secretion (AUCins/glu, HOMA-B), but lower insulin resistance-adjusted insulin secretion (ISS1-2) at 1 year." (PMID 37891561, 2023). "In addition, in response to its deterioration, the β cells will further increase insulin secretion, which exacerbates insulin resistance." (PMID 36985762, 2023). "Leptin can promote insulin resistance and downregulate insulin signaling in various cell models." (PMID 37780623, 2023). "Using KEGG pathway analysis, we find that indeed LPI-18:1 significantly induces a phosphopeptide signature associated with insulin signaling and insulin resistance in mice lacking MBOAT7 function in adipocytes (Mboat7ASKO mice)." (PMID 36806709, 2023). "Type 2 diabetes (T2D) is a chronic disease characterized by excessive levels of glucose in the blood resulting from the cells’ inability to respond to insulin, termed insulin resistance, and an inability of pancreatic beta cells to produce adequate levels of insulin." (PMID 37521964, 2023). "However, fasting insulin and insulin resistance index HOMA-IR remained lower in the post-TRF than in the HFD-AL group." (PMID 37299580, 2023). "Elevated insulin secretion reflects increased insulin resistance that is observed in the OBM group." (PMID 36991398, 2023). "Furthermore, the role of NADPH in lipid metabolism, particularly in the fatty acid synthesis pathway, ties it to the etiology of insulin resistance, where lipid accumulation and lipotoxicity are known to disrupt insulin signaling." (PMID 38203517, 2023). "High levels of calcium in the blood may interfere with b-cell secretory function as well as insulin signaling and glucose uptake in skeletal muscle and adipose tissue, ultimately leading to insulin resistance." (PMID 38104079, 2023).
Insulin resistance (continued). "According to this survey, the major feature of IRS is the presence of hyperinsulinemia (fasting serum insulin concentration of >30 μU/mL) with no apparent cause of insulin resistance, such as obesity or other conditions." (PMID 37042492, 2023). "Regular exercise is known to decrease insulin resistance and improve insulin sensitivity." (PMID 37924091, 2023). "In our previous observations, we utilized a 24 h recovery period (void of additional insulin) which may be necessary to reveal the accumulating effects of insulin resistance." (PMID 37367923, 2023). "Accumulated visceral fat and type 2 DM contribute to the development of HCC through various mechanisms, including inflammatory cytokines, several endocrine pathways, insulin resistance, hepatic lipotoxicity, hepatic and peripheral insulin resistance, and oxidative stress." (PMID 37380950, 2023). "In contrast, a recent investigation that employed the gold benchmark for determining peripheral insulin sensitivity discovered that vitamin D insufficiency was linked to the existence of obesity rather than insulin resistance." (PMID 37701195, 2023). "Oxidative stress can induce insulin resistance by impairing various insulin signaling." (PMID 37237539, 2023). "Moreover, the pathway analysis showed that insulin secretory, insulin resistance, apoptosis, and mitophagy pathways were enriched in the top 20 pathways of the Set 2 experiments." (PMID 37175791, 2023). "Many of these plant-based supplements examined in the articles included in this review likely have similar mechanisms for improving insulin sensitivity and thus more research into these supplements and potential implementation in dietary control of insulin resistance is needed." (PMID 36901197, 2023). "One possible explanation could be that treatment with anti-PCSK9 mAb determines a detectable improvement in hepatic insulin sensitivity only in those with a worse metabolic pattern, higher insulin resistance and BMI." (PMID 37324254, 2023). "However, treatment with orlistat and O. aristatus (200 mg/kg) for two months reduced the insulin resistance condition, and a similar pattern was indicated with the quantitative insulin-sensitivity check index (QUICKI)." (PMID 36678606, 2023). "In addition, increased levels of ROS also disturb the cascade of insulin-signaling, inspiring the development of insulin resistance." (PMID 36677055, 2023). "Moreover, apelin-deficient mice showed decreased plasma adiponectin, increased insulin, impaired glucose and insulin tolerance, and insulin resistance." (PMID 37424869, 2023). "The SPISE index is a surrogate marker for insulin resistance predicting emerging dysglycemia in children with overweight or obesity, and could, therefore, be applied to pediatric cohorts that lack direct insulin assessment." (PMID 36677025, 2023). "This leads to peripheral insulin resistance and impairment of pancreatic β-cell insulin secretion, while the adipocytes elevate adipokine secretion, NGF, interleukin 6 (IL-6), IL-1, tumor necrosis factor-α (TNF-α), and monocyte chemoattractant protein-1 (MCP-1)." (PMID 37373824, 2023). "Additionally, prolonged treatment with either low or high doses of clenbuterol has been observed to improve glucose and insulin tolerance in rodent models for insulin resistance and T2D." (PMID 38203312, 2023). "In conclusion, ATMP could promote insulin secretion and inhibit glucagon secretion, effectively improve glucose tolerance and alleviate insulin resistance." (PMID 36845056, 2023). "The hypothesis that COVID-19 is specifically related to hyperglycemia and recent-onset diabetes has even led to a search for effects directly mediated by the virus on the function and survival of insulin-producing beta cells and insulin resistance." (PMID 37193970, 2023).
Insulin resistance (continued). "Thus, oxidative stress is documented to interfere with the insulin signal transduction pathway, directly promote insulin resistance, and indirectly impede insulin signaling via mitochondrial damage and mitophagy." (PMID 38203642, 2023). "First, it can induce insulin resistance by inhibiting pathways related to renal insulin signaling." (PMID 37400794, 2023). "In regard to insulin resistance, some studies suggest that heightened amino acid levels in the blood intervene with insulin uptake via overactivation of the mTORC1 pathway, which increases phosphorylation of insulin receptor substrates and induces pancreatic beta cell dysfunction/degradation." (PMID 38068805, 2023). "Importantly, due to insulin resistance and elevated ratio of glucagon/insulin in obesity and T2DM, lipolysis would be increased in adipose tissue and a glycerol flux to the liver would occur, glycerol will be used as a preferred gluconeogenic precursor." (PMID 36836874, 2023). "In addition, elderly patients with insulin resistance show decreased insulin stimulation of mitochondrial protein synthesis and enzyme activity, resulting in decreased mitochondrial function." (PMID 36918975, 2023). "Inflammation disrupts insulin action and secretion, potentially contributing to insulin resistance." (PMID 37371912, 2023). "Finally, we investigate the target organ by which selective SSTR5 antagonists alleviate insulin resistance using a hyperinsulinemic‐euglycemic clamp technique in male KK‐Ay mice and measuring insulin‐induced Akt phosphorylation in male C57BL/6J mice." (PMID 36585794, 2023). "In addition to the connection with some lipid parameters, the results showed a positive association between MECPTP and ∑DBP and increased glucose and insulin levels, insulin resistance, and glycosylated hemoglobin (HbA1c)." (PMID 37367903, 2023). "Therefore, increasing insulin secretion from pancreatic beta cells to compensate for insulin resistance and maintain blood glucose levels is an important principle of T2D therapies." (PMID 37039251, 2023). "Obesity is a risk factor for insulin resistance (IR) that could result in type 2 diabetes mellitus (T2DM), associated with abnormal insulin secretion and finally chronic hyperglycemia." (PMID 36678151, 2023). "Indeed, acute critical illness is characterized by feeding-resistant catabolism and severe insulin resistance, especially in the liver, whereby endogenous glucose production cannot be suppressed by providing nutrients and insulin." (PMID 36707883, 2023). "The KEGG analysis also revealed decreased insulin resistance and insulin signaling pathways." (PMID 36879808, 2023). "Insulin resistance is defined as a decreased sensitivity and responsiveness to insulin." (PMID 36766803, 2023). "During pregnancy, the body becomes more resistant to insulin due to hormonal changes and PFAS exposure may exacerbates this insulin resistance, thereby increasing the risk of GDM." (PMID 37704943, 2023). "Insulin resistance can then, in turn, promote higher levels of circulating insulin." (PMID 38068805, 2023). "Additionally, several glucose metabolic biomarkers have shown a significant link to FIP, including glycated hemoglobin (HbA1c), fast insulin, homeostasis model assessment of insulin resistance (HOMA-IR), and fast glucose." (PMID 37809324, 2023). "Insulin resistance (IR) is a complex pathological state characterized by the impaired responsiveness of insulin-dependent cells, such as adipocytes and cardiomyocytes, to normal levels of circulating insulin." (PMID 38260171, 2023). "Removal of senescent cells using this mouse model on adult HFD mice (7-8 months) or mice with insulin resistance induced by S961 treatment, mitigates glucose intolerance, restores insulin sensitivity concomitant with a reduction in the markers of proinflammatory senescent β-cells in mouse islets." (PMID 37720527, 2023).
Insulin resistance (continued). "Visfatin is an insulin-mimetic adipocytokine that acts synergistically with insulin to enhance glucose uptake in vivo and in vitro and to inhibit the breakdown of liver glycogen into glucose, with insulin resistance-reducing and antidiabetic effects." (PMID 37432450, 2023). "However, during insulin resistance, the insulin sensitivity of these tissues is decreased, thus, resulting into a slightly elevated fasting blood glucose concentration." (PMID 38096150, 2023). "As expected, sleeve gastrectomy significantly (all p < 0.05) reduced body weight, total white adiposity and the adipokine leptin, as well as markers of insulin resistance (insulin and HOMA), independently of the diet provided after surgical intervention to the experimental animals." (PMID 36834823, 2023). "TNF can inhibit insulin-induced tyrosine phosphorylation of insulin receptor substrate 1 (IRS1) and glucose uptake, and promote degradation of the GKAP42 protein in adipocytes, thus causing T2DM and insulin resistance." (PMID 36747287, 2023). "Furthermore, SGLT2 inhibitors can reduce plasma glucose and insulin levels and show significant improvement in insulin resistance and insulin secretion." (PMID 36834946, 2023). "In another study, children with this characteristic presented higher concentrations of plasma insulin, elevated glycemia, increased insulin resistance, and diminished pancreatic production of insulin in comparison with individuals of the normal body mass index." (PMID 38107388, 2023). "Indeed, overexpression of NR4A nuclear receptors enhances overall insulin activity and improves insulin sensitivity during insulin resistance." (PMID 37715850, 2023). "Therefore, both T2DM and AD are intertwined through several characteristics, including chronic inflammation, oxidative stress, impaired insulin signaling, insulin resistance, glucose intolerance, and cognitive impairment." (PMID 36902074, 2023). "Moreover, a novel microbially produced small molecule imidazole propionate is involved in the impairment of insulin signalling by targeting the mammalian target of rapamycin complex 1 (mTORC1) and thus promoting glucose intolerance and insulin resistance." (PMID 37842639, 2023). "The oxidative burden in insulin resistance is characterized by an imbalance between pro-oxidants and antioxidant defenses, leading to the oxidative modification of cellular components, which further impairs insulin signaling." (PMID 38203517, 2023). "Moreover, M2 macrophages can play a crucial role in reducing insulin resistance, restoring insulin signaling, and optimizing the overall metabolism." (PMID 37511225, 2023). "Indeed, these animals kept or even increased the capacity to produce insulin, possibly to overcome insulin resistance, which characterizes the early stages of type 2 diabetes." (PMID 37237932, 2023). "In addition to the control of glucose and insulin responses, regulation of incretins is a potential therapeutic treatment option for insulin resistance." (PMID 36771483, 2023). "Furthermore, inflammatory macrophages were shown to impair hepatocyte responsiveness to insulin, thus promoting hepatic and systemic insulin resistance." (PMID 36994095, 2023). "However, in people with insulin resistance, fat cells become less responsive to insulin and are less able to take up glucose and store fat." (PMID 37600709, 2023). "Moreover, chronic low-grade inflammation contributes to the impairment in insulin signaling, thus leading to insulin resistance." (PMID 37755075, 2023). "In these individuals, excess fatty acid influx in the skeletal muscle and liver promotes diacylglycerol-induced insulin resistance, impairs insulin signaling via increased insulin receptor serine phosphorylation, and disrupts mitochondrial oxidative phosphorylation." (PMID 37834765, 2023). "Moreover, metformin decreased the plasma insulin level in ob/ob mice, indicated metformin alleviated the insulin resistance in ob/ob mice." (PMID 36645914, 2023).
Insulin resistance (continued). "This disruption may lead to insulin resistance, where the cells become less responsive to insulin, ultimately developing hyperinsulinemia." (PMID 38020199, 2023). "Furthermore, the sensitivity of the liver, muscle, and fat of T2DM patients to insulin is reduced, and the ability of the body to handle glucose is also significantly reduced, indicating obvious signs of insulin resistance and abnormal glucose tolerance." (PMID 37601073, 2023). "These factors include progressive insulin resistance and inadequate insulin secretory capacity." (PMID 37893486, 2023). "FFM, mainly included skeletal muscle, is the main site of insulin consumption, and low muscle mass may contribute to the development of insulin resistance (IR)." (PMID 37275645, 2023). "In addition, BCAAs are hormonal signalling regulators and are expected to module insulin resistance (IR) through increasing insulin secretion in human pancreatic β-cells." (PMID 37255970, 2023). "In a recent systematic review and meta-analysis, an association between preterm birth and higher homeostatic model assessment for insulin resistance (HOMA-IR) levels, a surrogate marker of insulin resistance, has been observed, together with increased fasting glucose and insulin levels." (PMID 37342257, 2023). "However, insulin resistance can dramatically reduce D-chiro-Ins synthesis in insulin-dependent organs, with resulting low intracellular levels of this inositol isomer." (PMID 37111094, 2023). "Experimental study shows that sEVs from bone marrow stem cells increase the gene expression of insulin signal pathway (insulin, Pdx1, Smad2, Smad3, and transforming growth factor β) in the type 1 diabetes condition and alleviate insulin resistance in the T2D rat model." (PMID 37593852, 2023). "ER stress and unfolded protein response play significant roles in insulin resistance aggravation through the activation of apoptosis, inflammatory response, and insulin signaling impairment mediated via IRE1/PERK/ATF6 signaling pathways and the upregulation of SREBP 1c." (PMID 37998747, 2023). "In addition, the presence of brain insulin resistance or any defects in the insulin signaling pathway in the FTD brain remains to be clarified." (PMID 37511207, 2023). "Likewise, the effects of the compounds on glucose tolerance, insulin resistance, as well as insulin and leptin levels, have been evaluated." (PMID 36901928, 2023). "Because of insulin resistance and impaired insulin signaling, patients with obesity and T2DM have low AKT activity and impaired phosphorylation of FOXO1and Crtc2 by AKT, leading to increased FOXO1 and Crtc2 protein levels that drive further gluconeogenic gene expressions." (PMID 36836874, 2023). "The submerged culture medium of CLM has been studied to control high blood glucose levels, insulin secretion via cell protective effect, antihyperglycemic efficacy by lowering insulin resistance, and insulin signal transduction via activation of AMPK and GLUT4." (PMID 36934269, 2023). "The DI represents the product of measures of insulin sensitivity and the acute insulin response to glucose (AIRg, an index of first-phase insulin secretion), thus expressing the ability of β-cells to compensate for augmented insulin resistance with changes in the first-phase secretion." (PMID 37836486, 2023). "Studies in SAs have highlighted that high insulin concentrations and/or insulin resistance may exaggerate the postprandial TAG response by inhibiting the normal suppressive action of insulin on hepatic very-low-density-lipoprotein production." (PMID 36729923, 2023). "While T1DM results from a complete lack of insulin production in the body, and gestational DM occurs during pregnancy due to insulin resistance caused by hormonal changes, T2DM is primarily characterized by the ineffective use of produced insulin, and its prevalence is increasing worldwide." (PMID 38131849, 2023).